RNU7-111P (RNA, U7 small nuclear 111 pseudogene)
Gene: Small nuclear RNA gene on chromosome 15 (89,897,576 to 89,897,637, forward strand). Ensembl gene ENSG00000252645.
Homologues: Orthologues: macaque U7 (97% identical). Paralogues in human: RNU7-110P (84% identical), RNU7-35P (84% identical), RNU7-97P (84% identical), RNU7-167P (82% identical), RNU7-41P (82% identical), U7 (82% identical), RNU7-123P (81% identical), RNU7-124P (81% identical), RNU7-138P (81% identical), RNU7-18P (81% identical), RNU7-40P (81% identical), RNU7-6P (81% identical), and 143 more.